SACK1B (scaffolding CK1 anchoring protein B)
Description:
Probable proto-oncogene that functions in the epidermal growth factor receptor/EGFR signaling pathway. Activates both the EGFR itself and downstream RAS/MAPK and PI3K/AKT/TOR signaling cascades.
Synonyms: FAM83B; C6orf143; FLJ30642
Tractability: Small molecule: a structure with a bound ligand is known. PROTAC: ubiquitination databases record sites on it.
Gene: Protein-coding gene on chromosome 6 (54,846,771 to 54,945,099, forward strand). Ensembl gene ENSG00000168143.
Subcellular location: Cytoplasm; Membrane
Pathways (Reactome):
Signal Transduction: RND1 GTPase cycle; RND2 GTPase cycle; RND3 GTPase cycle; Signaling by EGFR
Gene Ontology:
Molecular function: epidermal growth factor receptor binding; phosphatidylinositol 3-kinase catalytic subunit binding; phosphatidylinositol 3-kinase regulatory subunit binding; phospholipase D activity; protein binding; protein kinase binding
Biological process: cell population proliferation; positive regulation of epidermal growth factor receptor signaling pathway; signal transduction
Cellular component: cytoplasm; membrane; cytosol
Genetic constraint (gnomAD): Loss-of-function variants: 32 observed, 46.99 expected, observed/expected ratio (o/e) 0.68, 90% interval 0.51 to 0.92. The upper end of that interval is the gene's LOEUF score, 0.92, which puts it in group 3 of 6, group 1 being the genes least tolerant of losing a copy. Missense variants: 1,206 observed, 1,214.3 expected, observed/expected ratio (o/e) 0.99, 90% interval 0.95 to 1.04. Synonymous variants: 411 observed, 433.38 expected, observed/expected ratio (o/e) 0.95, 90% interval 0.87 to 1.03.
Homologues: Orthologues: chimpanzee FAM83B (99% identical), macaque FAM83B (97% identical), dog FAM83B (89% identical), pig FAM83B (85% identical), rabbit FAM83B (85% identical), rat Fam83b (82% identical), mouse Fam83b (81% identical), guinea pig FAM83B (80% identical), tropical clawed frog fam83b (53% identical), zebrafish fam83b (34% identical). Paralogues in human: SACK1H (20% identical), SACK1G (15% identical), SACK1C (14% identical), SACK1D (14% identical), SACK1F (13% identical), SACK1E (13% identical), SACK1A (11% identical).
Diseases named in the same sentence as SACK1B in open-access papers:
SACK1B is named in the same sentence as 33 diseases in open-access papers, as found by Europe PMC text mining. Sharing a sentence is not in itself a finding about the gene and the disease.
SACK1B shares sentences with these, for which no sentence is quoted: tumor (19 papers); cancer (18); gastric cancer (13); lung carcinoma (7); breast carcinoma (6); ovarian carcinoma (5); lung squamous cell carcinoma (4); cervical cancer (3); endometrial cancer (3); lung adenocarcinoma (3); non-small cell lung carcinoma (3); pancreatic ductal adenocarcinoma (3); adenocarcinoma (2); gastric adenocarcinoma (2); lymphoid cancer (2); pancreatic cancer (2); papillary thyroid cancer (2); squamous carcinoma (2); thyroid cancer (2); anaplastic thyroid cancers (1); bladder cancer (1); breast tumor (1); cervical adenocarcinoma (1); cervical squamous cell carcinoma (1); colorectal cancer (1); follicular thyroid cancers (1); lymph node metastasis (1); osteosarcoma (1); ovarian tumor (1); Parkinson disease (1).
A further 3 diseases each share a sentence with SACK1B in 1 paper.